EFEMP2 (EGF-like fibulin extracellular matrix protein 2)
Description:
Plays a crucial role in elastic fiber formation in tissue, and in the formation of ultrastructural connections between elastic laminae and smooth muscle cells in the aorta, therefore participates in terminal differentiation and maturation of smooth muscle cell (SMC) and in the mechanical properties and wall integrity maintenance of the aorta. In addition, is involved in the control of collagen fibril assembly in tissue throught proteolytic activation of LOX leading to cross-linking of collagen and elastin (By similarity). Also promotes ELN coacervation and participates in the deposition of ELN coacervates on to microfibrils but also regulates ELN cross-linking through LOX interaction. Moreover adheres to the cells through heparin binding in a calcium-dependent manner and regulates vascularlar smooth muscle cells proliferation through angiotensin signaling.
Synonyms: FBLN4; UPH1; ARCL1B; MBP1
Tractability: Antibody: UniProt places it where antibodies can reach, with high confidence; its Gene Ontology location is reachable by antibodies, with high confidence; UniProt predicts a signal peptide or a membrane-spanning region.
Gene: Protein-coding gene on chromosome 11 (65,866,441 to 65,878,497, reverse strand). Ensembl gene ENSG00000172638.
Subcellular location: Secreted, extracellular space, extracellular matrix; Secreted, extracellular space, extracellular matrix, basement membrane
Pathways (Reactome):
Extracellular matrix organization: Molecules associated with elastic fibres
Gene Ontology:
Molecular function: heparin binding; protein binding; protein homodimerization activity; extracellular matrix structural constituent; calcium ion binding
Biological process: elastic fiber assembly; positive regulation of smooth muscle cell-matrix adhesion; aorta development; aorta smooth muscle tissue morphogenesis; negative regulation of vascular associated smooth muscle cell proliferation; positive regulation of aortic smooth muscle cell differentiation; positive regulation of collagen fibril organization; regulation of collagen fibril organization; vascular associated smooth muscle cell development
Cellular component: elastic fiber; extracellular exosome; extracellular matrix; extracellular vesicle; basement membrane; extracellular region; non-collagenous component of interstitial matrix
Genetic constraint (gnomAD): Loss-of-function variants: 21 observed, 54.03 expected, observed/expected ratio (o/e) 0.39, 90% interval 0.28 to 0.56. The upper end of that interval is the gene's LOEUF score, 0.56, which puts it in group 2 of 6, group 1 being the genes least tolerant of losing a copy. Missense variants: 513 observed, 630.4 expected, observed/expected ratio (o/e) 0.81, 90% interval 0.76 to 0.88. Synonymous variants: 275 observed, 250.36 expected, observed/expected ratio (o/e) 1.1, 90% interval 1 to 1.21.
Gene-disease validity (ClinGen):
ClinGen rates the evidence that EFEMP2 causes each of these diseases.
cutis laxa, autosomal recessive, type 1B (autosomal recessive): Definitive.
Homologues: Orthologues: chimpanzee EFEMP2 (99% identical), macaque EFEMP2 (99% identical), dog EFEMP2 (97% identical), guinea pig EFEMP2 (96% identical), mouse Efemp2 (95% identical), pig EFEMP2 (85% identical), rat Efemp2 (83% identical), tropical clawed frog efemp2 (72% identical), zebrafish efemp2a (68% identical), zebrafish efemp2b (65% identical). Paralogues in human: EFEMP1 (53% identical), FBLN5 (49% identical), FBLN2 (38% identical), FBLN1 (37% identical), EYS (28% identical), VWDE (22% identical).
Diseases named in the same sentence as EFEMP2 in open-access papers:
EFEMP2 is named in the same sentence as 86 diseases in open-access papers, as found by Europe PMC text mining. Sharing a sentence is not in itself a finding about the gene and the disease. The quoted sentences say what the papers report.
cutis laxa (15 papers, 2007 to 2026). Cutis laxa (CL) is an inherited or acquired connective tissue disorder characterized by wrinkled, redundant and sagging inelastic skin associated with skeletal and developmental anomalies and, in some cases, with severe systemic involvement. "This disorder is also known as Autosomal Recessive Cutis Laxa Type 1B (OMIM: 614437) as missense mutations in EFEMP2 have also been shown to have impaired secretion and binding, and increased proteolysis leading to Cutis Laxa." (PMID 39480826, 2024). "For an EFEMP2 homozygous missense variant, postnatal clinical examination confirmed cutis laxa, with the knowledge of a similar phenotype in a previously deceased fetus, highly suggestive of an autosomal recessive disorder in a consanguineous family." (PMID 37035737, 2023). "Mutations in EFEMP2 have been associated with cutis laxa, an autosomal recessive disorder of connective tissue characterized by inelastic tissue in all affected areas of the body." (PMID 22919265, 2012). "Cutis laxa (EFEMP2) and Hermansky-Pudlak syndrome (DTNBP1)-related genes were enriched in mast cells." (PMID 32727470, 2020). "ATS should be differentiated from EFEMP2-related cutis laxa, Loeys-Dietz syndrome, Ehlers-Danlos syndrome, FBLN5-related cutis laxa, LTBP4-related cutis laxa and Occipital horn syndrome." (PMID 34384376, 2021).
aneurysm (13 papers, 2011 to 2025). Bulging or ballooning in an area of an artery secondary to arterial wall weakening. "Homozygous or compound heterozygous mutations in the gene for ECM protein Fibulin-4, EFEMP2, cause cutis laxa syndrome (ARCL1B; MIM 614437) in patients, characterized by systemic connective tissue abnormalities, including loose skin, lung emphysema, bone fragility, vascular tortuosity and aneurysms." (PMID 35492343, 2022).
glioma (10 papers, 2016 to 2024). A benign or malignant brain and spinal cord tumor that arises from glial cells (astrocytes, oligodendrocytes, ependymal cells). "Since it has been widely recognized that IDH1 mutation is a critical driver of low grade glioma, we explored the relationship between EFEMP2 transcription level and IDH1 mutation." (PMID 32396873, 2020). "On the contrary, in cancers, such as ovarian cancer, glioma, osteosarcoma, and aneurysm, EFEMP2 is highly expressed, considered a candidate oncogene, and associated with poor prognosis of the tumors." (PMID 37420173, 2023). "It was observed that the resting macrophage, as a feature of malignancy of GBM, revealed a distinct assembly in glioma with high levels of EFEMP2, supporting EFEMP2′s role as a marker of assembly of M0 macrophage and more malignant phenotypes of glioma." (PMID 34071306, 2021). "Of these, ten genes (CTSZ, EFEMP2, ITGA5, KDELR2, MDK, MICALL2, MAP 2 K3, PLAUR, SERPINE1 and SOCS3) can potentially classify patients with gliomas into different risk groups." (PMID 32878880, 2020). "To ask if EFEMP2 is involved in malignant progress of glioma, we compared its expression levels in different WHO grades in CGGA mRNA sequencing dataset, TCGA mRNA sequencing dataset of glioma, GSE16011 and REMBRANDT datasets." (PMID 32396873, 2020). "When the cluster number was set as 4, the top 20 glioma samples with highest expression of EFEMP2 specifically gathered with M0 phenotype." (PMID 32396873, 2020). "Now we found that high expression of EFEMP2 not only remarkably reflected a more malignant phenotype of glioma, but also indicated assembly of M0-like macrophage." (PMID 32396873, 2020). "We evaluated the expression of EFEMP2 in human glioma specimens and observed that EFEMP2 was indeed highly expressed in GBM specimens (Figure." (PMID 32396873, 2020). "The distinct correlation of EFEMP2 expression level and assembly of M0 cells implied the role of EFEMP2 in governing the fates of macrophages infiltrated into glioma." (PMID 32396873, 2020). "Except for Classical subtype in GSE16011, glioma with wild type IDH1 harbored higher EFEMP2 transcriptional levels in each subtype of these three datasets." (PMID 32396873, 2020). "EFEMP2 (EGF-containing fibulin-like extracellular matrix protein 2) is crucial in shaping the tumour microenvironment, markedly influencing overall survival and tumour-associated macrophage dynamics in glioma." (PMID 39063109, 2024). "While mutations in EFEMP2, ADAM10, SERPINH1, ADAM15, GAS6 and TNXB were detected only in patients with glioma grade 3, mutations in LTBP2, DCN, CRELD1 and HAPLN3 were observed only in patients with glioma grade 4, GBM." (PMID 38272115, 2024). "EFEMP2 has also been considered as a potential biomarker for colorectal cancer and glioma subtypes." (PMID 37420173, 2023). "Based on the pro-tumorigenic features of EFEMP2 in other tumors and our analysis in glioma, we propose that EFEMP2 might be used as a marker of the glioma subtype enriched of M0 macrophage." (PMID 32396873, 2020). "The correlation between EFEMP2 expression and glioma subtypes could also reflect the oncogenic characteristics of EFEMP2." (PMID 32396873, 2020). "EFEMP2 was found highly expressed in glioma of higher WHO grade and Mesenchymal subtype glioma, and its transcriptional level could predict OS efficiently in validation datasets." (PMID 32396873, 2020). "In vitro assay showed that EFEMP2’s level in medium was closely related to glioma cells’ growth." (PMID 32396873, 2020). "EFEMP2 is upregulated in gliomas and promotes glioma cell proliferation and invasion." (PMID 29740513, 2018). "The coincidences of high-EFEMP2-expression with the classical genetic alterations indicating malignancy, and the exclusivity of high-EFEMP2-expression with the indicator of positive prognosis descripted the oncogenic nature of EFEMP2 which is closely correlated to malignant phenotypes of glioma." (PMID 32396873, 2020).
glioma (continued). "Kaplan-Meier analyses based on TCGA mRNA array or sequencing data of glioma, GSE16011 and REMBRANDT confirmed the OS distinguishing effects of EFEMP2 expression levels." (PMID 32396873, 2020). "The patients with both LGG (low-grade glioma) and HGG (high-grade glioma) or only HGG (WHO III and IV grade) were divided into two groups upon their EFEMP2 expression level derived from CGGA mRNA array." (PMID 32396873, 2020). "EFEMP2 expression level was sufficient to predict overall survival (OS) and progression-free survival (PFS) of patients with glioma in four datasets." (PMID 32396873, 2020). "Here we proposed an OS (overall survival)-correlated gene EFEMP2 (EGF containing fibulin-like extracellular matrix protein 2) via screening with transcriptional expression levels and methylation data in two glioma databases." (PMID 32396873, 2020). "The half of patients with higher EFEMP2 expression exhibited shorter OS and PFS in either all grades or HGG glioma." (PMID 32396873, 2020). "Although never described in glioma studies, EFEMP2, and GNAO1 are reported in pathway databases to be also involved with phospholipase-C (PLC) activity." (PMID 38812741, 2024).
osteosarcoma (8 papers, 2018 to 2025). A usually aggressive malignant bone-forming mesenchymal neoplasm, predominantly affecting adolescents and young adults. "Given that the relationship between STEAP proteins and osteosarcoma remains largely unknown, we used the data to develop a set of experiments designed to determine whether STEAP2 promotes the development of osteosarcoma and whether these functions are linked to EFEMP2 activity in these cells." (PMID 36316642, 2022). "Our previous study revealed that EFEMP2 facilitates osteosarcoma infiltration and migration via its activation of the PI3K/Akt/mTOR axis and that changes in EFEMP2 expression induce similar changes in STEAP2 expression." (PMID 36316642, 2022). "This was then validated by the fact that overexpression of STEAP2 in EFEMP2 shRNA-transfected osteosarcoma cells increases the invasive capacity of these cells even in the absence of EFEMP2." (PMID 36316642, 2022). "STEAP2 is also overexpressed in highly invasive osteosarcoma and subclone cell lines, and similar to EFEMP2, it also induces EMT through the PI3K/AKT/mTOR axis." (PMID 36316642, 2022). "These experiments demonstrated that a reduction in either STEAP2 or Akt or both inhibited EMT and PI3K/Akt/mTOR axis activation in osteosarcoma cells even when treated with exogenous EFEMP2." (PMID 36316642, 2022). "Given these outcomes, this study mainly evaluated the roles of STEAP2 in osteosarcoma, its value as biomarker, and its specific interaction with EFEMP2, to better understand osteosarcoma pathogenesis." (PMID 36316642, 2022). "Our data, thus, suggest that EFEMP2 partly targets STEAP2 to promote osteosarcoma progression by inducing EMT via the PI3K/AKT/mTOR axis." (PMID 36316642, 2022). "We found that inhibition of STEAP2 or Akt expression via RNA interference prevents osteosarcoma cell invasion induced by the endogenous or exogenous overexpression of EFEMP2." (PMID 36316642, 2022). "In this study, we clearly show that changes in EFEMP2 expression directly affect STEAP2 expression in osteosarcoma." (PMID 36316642, 2022). "We validated this hypothesis by treating less invasive osteosarcoma MG63-31 cells with purified EFEMP2 (100, 200, and 300 ng/ml) for 24 h." (PMID 36316642, 2022). "Thus, downregulation of STEAP2 or Akt blocks EFEMP2-mediated induction of the EMT process in osteosarcoma cells." (PMID 36316642, 2022). "EFEMP2 is also likely to partly target STEAP2 to promote osteosarcoma progression." (PMID 36316642, 2022). "Taken together, these findings indicate that EFEMP2 likely regulates EMT and activates the PI3K/AKT/mTOR axis by targeting STEAP2, thereby facilitating osteosarcoma cell infiltration and migration." (PMID 36316642, 2022). "To our knowledge, this is the first study to explore the relationship between STEAP2 and osteosarcoma, and similar to EFEMP2 expression, we found that STEAP2 was also highly expressed in osteosarcoma and likely to affect EMT through the PI3K/AKT/mTOR axis." (PMID 36316642, 2022). "Changes in EFEMP2 expression resulted in correlating changes in STEAP2 expression, with EFEMP2-overexpressing osteosarcoma cells exhibiting a less invasive phenotype and reduced EMT following STEAP2 inhibition." (PMID 36316642, 2022). "To date, there has been little investigation into the up- and downstream mechanisms controlling EFEMP2 and STEAP2 expression; however, this work suggests that these mechanisms may have a significant impact on the treatment of osteosarcoma." (PMID 36316642, 2022). "Thus, we can conclude that STEAP2 acts as an oncogene in osteosarcoma progression, while EFEMP2 enables PI3K/AKT/mTOR axis initiation and EMT by partly targeting STEAP2, thereby facilitating osteosarcoma cell infiltration and migration." (PMID 36316642, 2022).
osteosarcoma (continued). "Taken together, these data suggest that EFEMP2 induces EMT and initiates the PI3K/Akt/mTOR axis partly via its interaction with STEAP2, thereby enhancing the migratory and invasive capacities of osteosarcoma cells and promoting the development of osteosarcoma." (PMID 36316642, 2022). "Based on these experimental results, we hypothesize that osteosarcoma cells secrete excessive EFEMP2, which in turn targets STEAP2 initiating the PI3K/Akt/mTOR axis and inducing EMT which in turn enhances osteosarcoma cell infiltration and migration." (PMID 36316642, 2022). "Give this, we hypothesized that EFEMP2 is closely related to STEAP2, and further experimental results revealed that knockdown of STEAP2 expression in EFEMP2 cDNA-transfected osteosarcoma cells significantly reduced the increased invasive capacity conferred by EFEMP2 overexpression." (PMID 36316642, 2022). "In addition, our data shows that the overexpression of this protein increases infiltration and migration and that EFEMP2 initiates the Akt pathway triggering EMT via its direct regulation of STEAP2, thereby intensifying the migratory and invasive capacities of osteosarcoma cells." (PMID 36316642, 2022). "In addition, similar to EFEMP2, STEAP2 may induce EMT through the PI3K/AKT/mTOR axis and facilitate osteosarcoma cell infiltration and migration." (PMID 36316642, 2022). "It is also worth noting that although EFEMP2 overexpression activated the PI3K/AKT/mTOR pathway promoting EMT, it did not affect osteosarcoma cells in which STEAP2 or Akt was knocked down." (PMID 36316642, 2022). "Similarly, repression of STEAP2 reversed the effect of EFEMP2 overexpression, and exogenous EFEMP2 activated the Akt pathway and EMT process in osteosarcoma cells but had no impact on cells with reduced STEAP2 or Akt expression." (PMID 36316642, 2022).
breast carcinoma (7 papers, 2019 to 2025). "Besides the role played by ITGA5 in promoting breast cancer cell adhesion, invasion, and survival, EFEMP2, KIAA1199, and MFAP5 also enhance breast cancer motility and invasiveness." (PMID 33420367, 2021). "Inversely, the expression of EFEMP2 in breast cancer tissues was significantly lower than that in adjacent tissues, and its expression was negatively correlated with breast cancer tumor grade, suggesting that EFEMP2 can be used as an independent predictor of breast cancer prognosis." (PMID 31592144, 2019). "Here, we identified fibulin-4 (FBLN4), also known as EFEMP2, as the protein target for BLMP6 binding and show that FBLN4 is highly expressed in invasive and metastatic human breast cancer." (PMID 40611893, 2025). "Specifically, TOM1L1 and ESR1 were highly expressed, but MAFF, TNS1, EFEMP2, and TRIM31 were significantly downregulated in breast cancer." (PMID 34151731, 2021). "EFEMP2 significantly inhibits the invasion and metastasis of tumor cells and the process of epithelial-mesenchymal transition (EMT) through the Wnt/β-catenin pathway in lung, bladder, and breast cancers." (PMID 33718128, 2021).
cervical carcinoma (7 papers, 2019 to 2024). A carcinoma arising from either the exocervical squamous epithelium or the endocervical glandular epithelium. "So far, the role of EFEMP2 in tumorigenesis is found to be “context-specific”; indeed, while in cervical cancer, ovarian cancer, and glioblastoma it has been associated with tumor progression and poor prognosis, in endometrial cancer it has been found to inhibit EMT, tumor invasion and metastasis." (PMID 36945054, 2023). "In cervical carcinoma, high EFEMP2 expression is associated with lymph node metastasis and poor prognosis in patients, and high expression of EFEMP2 may promote angiogenesis." (PMID 31592144, 2019). "Another study showed that EFEMP2 was highly expressed in highly invasive cervical cancer cells Ca-Ski, and the up-regulation of EFEMP2 expression could further promote the proliferation and invasion of cervical cancer cells by inducing EMT through activation of Raf/MEK/ERK pathway." (PMID 37420173, 2023). "Finally, we identified that the model constructed by GIMAP4, GIMAP1, FGF13-AS1, EFEMP2, and DYNC2I2 could be used as the prediction model for the prognosis of cervical cancer." (PMID 35782114, 2022).
emphysema (6 papers, 2012 to 2023). "Overall, our findings suggest that pulmonary EFEMP2 expression is associated with emphysema in both humans and mice." (PMID 37400563, 2023). "The ME mouse is a model of mild, accelerated aging with low-inflammatory emphysema and respiratory dysfunction that progresses with age and pulmonary EFEMP2 decrease, similar to that observed in patients with mild COPD." (PMID 37400563, 2023). "Further investigation of the decrease in EFEMP2 expression is required to elucidate its contribution to the development of emphysema with and without cigarette smoke-mediated inflammation." (PMID 37400563, 2023). "Pulmonary EFEMP2 deficiency constitutes one of the molecular characteristics of emphysema in ME mice, similar to that observed in patients (those with mild COPD had less pulmonary arterial EFEMP2 than those without COPD)." (PMID 37400563, 2023).